MT-RNR2 (mitochondrially encoded 16S rRNA)
Description:
Significantly reduces apoptosis and the generation of reactive oxygen species and improves mitochondrial metabolism in vitro. Reduces gentamicin-induced cochlear hair cell loss in vitro by decreasing activation of AKT and AMPK alpha as well as reducing oxidative stress and decreasing levels of pro-inflammatory cytokines IL1B and IL6 in hair cells. Plays a role as a neuroprotective factor. Protects against neuronal cell death induced by multiple different familial Alzheimer disease genes and amyloid-beta proteins in Alzheimer disease. Mediates its neuroprotective effect by binding to the humanin receptor complex; binding of MT-RNR2 activates the intracellular JAK-STAT3 signaling pathways. Also acts as a ligand for G protein-coupled receptors FPR2/FPRL1 and FPR3/FPRL2. Inhibits amyloid-beta protein 40 fibril formation. Also inhibits amyloid-beta protein 42 fibril formation. Suppresses apoptosis by binding to BAX and preventing the translocation of BAX from the cytosol to mitochondria. Also suppresses apoptosis by binding to BID and inhibiting the interaction of BID with BAX and BAK which prevents oligomerization of BAX and BAK and suppresses release of apoptogenic proteins from mitochondria. Forms fibers with BAX and also with BID, inducing BAX and BID conformational changes and sequestering them into the fibers which prevents their activation. Can also suppress apoptosis by interacting with BIM isoform BimEL, inhibiting BimEL-induced activation of BAX, blocking oligomerization of BAX and BAK, and preventing release of apoptogenic proteins from mitochondria. Plays a role in up-regulation of anti-apoptotic protein BIRC6/APOLLON, leading to inhibition of neuronal cell death. Binds to IGFBP3 and specifically blocks IGFBP3-induced cell death. Competes with importin KPNB1 for binding to IGFBP3 which is likely to block IGFBP3 nuclear import. Induces chemotaxis of mononuclear phagocytes via FPR2/FPRL1. Reduces aggregation and fibrillary formation by suppressing the effect of APP on mononuclear phagocytes and acts by competitively inhibiting the access of FPR2 to APP. Protects retinal pigment epithelium (RPE) cells against oxidative stress-induced and endoplasmic reticulum (ER) stress-induced apoptosis. Promotes mitochondrial biogenesis in RPE cells following oxidative stress and promotes STAT3 phosphorylation which leads to inhibition of CASP3 release. Also reduces CASP4 levels in RPE cells, suppresses ER stress-induced mitochondrial superoxide production and plays a role in up-regulation of mitochondrial glutathione. Reduces testicular hormone deprivation-induced apoptosis of germ cells at the nonandrogen-sensitive stages of the seminiferous epithelium cycle. Protects endothelial cells against free fatty acid-induced inflammation by suppressing oxidative stress, reducing expression of TXNIP and inhibiting activation of the NLRP3 inflammasome which inhibits expression of pro-inflammatory cytokines IL1B and IL18. Protects against high glucose-induced endothelial cell dysfunction by mediating activation of ERK5 which leads to increased expression of transcription factor KLF2 and prevents monocyte adhesion to endothelial cells. Inhibits the inflammatory response in astrocytes. Increases the expression of PPARGC1A/PGC1A in pancreatic beta cells which promotes mitochondrial biogenesis. Increases insulin sensitivity. Significantly increases apoptosis in vitro. Binds to and activates chemokine receptor ACKR3/CXCR7 which results in activation of proopiomelanocortin neurons in the arcuate nucleus of the hypothalamus, leading to suppression of food intake and increased energy expenditure. Displays chaperone-like activity, inhibiting misfolding of IAPP and preventing IAPP amyloid formation. Significantly reduces apoptosis and the generation of reactive oxygen species and improves mitochondrial metabolism in vitro. Promotes cell proliferation in vitro.
Synonyms: HN; 16S; formerly MTRNR2
Gene: Mitochondrial ribosomal RNA gene on chromosome MT (1,671 to 3,229, forward strand). Ensembl gene ENSG00000210082.
Subcellular location: Secreted; Cytoplasm; Cell projection, cilium, flagellum; Nucleus; Mitochondrion; Mitochondrion inner membrane
Pathways (Reactome):
Metabolism of RNA: FASTK family proteins regulate processing and stability of mitochondrial RNAs; Mitochondrial RNA degradation; rRNA modification in the mitochondrion; rRNA processing in the mitochondrion; tRNA processing in the mitochondrion
Metabolism of proteins: Mitochondrial ribosome-associated quality control; Mitochondrial translation elongation; Mitochondrial translation initiation; Mitochondrial translation termination
Gene Ontology:
Molecular function: structural constituent of ribosome
Cellular component: ribosome
Gene-disease validity (ClinGen):
ClinGen rates the evidence that MT-RNR2 causes each of these diseases.
mitochondrial disease (mitochondrial): Limited.
Diseases named in the same sentence as MT-RNR2 in open-access papers:
MT-RNR2 is named in the same sentence as 63 diseases in open-access papers, as found by Europe PMC text mining. Sharing a sentence is not in itself a finding about the gene and the disease. The quoted sentences say what the papers report.
Alzheimer disease (12 papers, 2009 to 2025). A progressive, neurodegenerative disease characterized by loss of function and death of nerve cells in several areas of the brain leading to loss of cognitive function such as memory and language. "Humanin is a 21–24 aa peptide encoded by the mitochondrial MT-RNR2 gene encoding 16S rRNA discovered in surviving neurons in patients with Alzheimer’s disease." (PMID 37709773, 2023). "The MT-RNR2 gene also encodes the Humanin polypeptide that has been the target of Alzheimer's disease research and is found to be regulated on eight sites by two miRNA, namely, hsa-miR-mit4 and hsa-miR-mit3." (PMID 25695052, 2015). "MT-RNR2 gene, which is responsible for Alzheimer's disease, is also found to be under regulation of three miRNA, that is, hsa-miR-mit3, hsa-miR-mit6, and hsa-miR-mit4." (PMID 25695052, 2015).
diabetes (9 papers, 2011 to 2025). "Taking into account that the entire haplogroup H is characterized by another base substitution in MTRNR2 (G2706A), it is conceivable that such a combination of polymorphisms in the same gene might modulate susceptibility to diabetes." (PMID 21695278, 2011).
lung carcinoma (6 papers, 2019 to 2024). "Therefore, MT1 and MTRNR2 interactions may play an important role in lung cancer development." (PMID 34564354, 2021).
type 2 diabetes (4 papers, 2011 to 2026). "In conclusion, our data appear to indicate that mitochondrial backgrounds do not play a significant role in causing the onset of type 2 diabetes, despite indications of a protective effect for haplogroup H1 – possibly due to the G3010A transition in the MTRNR2 gene." (PMID 21695278, 2011).
breast carcinoma (3 papers, 2020 to 2023). "Also, we suggest that the expression level of XIST and MT-RNR2 in the human breast cancer and GC patients to evaluate the accurate expression pattern of these gene and lncRNA in the patients." (PMID 35581633, 2022).
glioblastoma (2 papers, 2023 to 2025). The most malignant astrocytic tumor (WHO grade IV). "These are isoforms of the MT-RNR2 gene, which encodes Humanin—a small peptide with neuroprotective and antiapoptotic activity in neuroblasts of Alzheimer’s diseased brains—and has recently been attributed with oncogenic effects in glioblastoma cells 50–52." (PMID 39891579, 2025).
hepatocellular carcinoma (2 papers, 2022 to 2023). A malignant tumor that arises from hepatocytes. "SNP presence on two noncoding genes (MT-RNR1 and MT-RNR2) encoded by mitochondrial DNA, mainly responsible for mitochondrial protein synthesis, were found to act as prognostic markers especially in hepatocellular carcinoma; the poor prognosis of HCC is largely due to high rates of tumor metastasis." (PMID 36832301, 2023).
bladder cancer (1 paper, 2022). "MT-RNR2, upregulated in both 1321N1 and LN18 cells, is linked to anti-apoptotic activities in bladder cancer." (PMID 35392560, 2022).
coronary artery disease (1 paper, 2023). "While there is uncertainty as to whether it is a transcribed protein-coding gene or a paralog of the mitochondrial gene MT-RNR2, several recent studies have identified its potential involvement in coronary artery disease, tumorigenesis, Huntington’s disease, and diabetic kidney disease." (PMID 37686214, 2023).
emphysema (1 paper, 2022). "miR4485-3p had a different expression pattern than the studied MT-RNR2-derived rRNAs, and its levels were increased in ATII cells obtained from both smokers and emphysema patients." (PMID 35884802, 2022).
familial hypertrophic cardiomyopathy (1 paper, 2023). Hypertrophic cardiomyopathy caused by mutations in the genes encoding components of the sarcomere, in the absence of predisposing conditions. "The authors described the effects of DNJ in restoring mitochondria and preventing cardiac myocyte hypertrophy in cellular models carrying a mutant mitochondrial gene, MT-RNR2, which is causally implicated in familial hypertrophic cardiomyopathy." (PMID 37463442, 2023).
hearing (1 paper, 2015). "In order to study the prevalence of mutations in MT-RNR1 and MT-RNR2 genes among Finnish children, we studied a ten-year cohort of hearing impaired children born in Northern Finland." (PMID 25650108, 2015).
Hodgkins lymphoma (1 paper, 2024). A heterogeneous group of malignant lymphoid neoplasms of B-cell origin characterized histologically by the presence of Hodgkin and Reed-Sternberg (HRS) cells in the vast majority of cases. "In humans, the mutation in MT-RNR2 encoding for 16S rRNA (m.1728 G > A) was also associated with the increase of tumorigenic potential of Hodgkin lymphoma cells." (PMID 39261587, 2024).
ototoxicity (1 paper, 2022). damage to the ear, specifically the cochlea or auditory nerve as a result of some toxic stimulus, eg from a drug. "The polymorphisms in the MT-RNR1 and MT-RNR2 genes were associated with increased mitochondrial and clinical adverse effects, most commonly ototoxicity and peripheral neuropathy." (PMID 34980117, 2022).
Q fever (1 paper, 2019). A bacterial infection caused by Coxiella burnetii. "It is intriguing that MT-RNR1 and MT-RNR2 were less expressed in asymptomatic Q fever seropositive controls, albeit to a lesser extent than in QFS and CFS patients." (PMID 31088495, 2019).
rectal cancer (1 paper, 2022). A primary or metastatic malignant neoplasm that affects the rectum. "In further support of our assumption, a base deletion in a ribosomal subunit gene (MT-RNR2) pivotal for the mitochondrial protein synthesis was associated with the likelihood of inferior outcome in this population of rectal cancer patients prone to metastatic progression." (PMID 34961902, 2022).
sarcoma (1 paper, 2024). A usually aggressive malignant neoplasm of the soft tissue or bone. "Notably, MTRNR2L12 (humanin‐like 12), derived from the mitochondrial gene MT‐RNR2, was markedly diminished in monocytes, T cells, SMCs, and ECs, indicating altered mitochondrial function within the sarcoma microenvironment." (PMID 39658531, 2024).
tumor (17 papers, 2010 to 2025). "MT-RNR2 also encodes a conserved cyto-protective polypeptide called humanin that promote tumor progression and metastasis by its anti-apoptotic effects." (PMID 40374694, 2025). "Among those, only the mutation of gene MT-RNR2 at position 2602 of the mitochondria chromosome is replicated in both primary tumor and lymph node." (PMID 31028395, 2019). "In patient #3, a small number of cells without clear CNVs (D-type) from tumor tissues clustered with adjacent normal cells based on transcriptome data, and these cells did not have mutations in MT-RNR2 (chrM:3004), which was shared by tumor cells with clear CNVs." (PMID 35974387, 2022).
cancer (11 papers, 2014 to 2025). A tumor composed of atypical neoplastic, often pleomorphic cells that invade other tissues. "In addition, cancer cells in SN upregulated MT-RNR2, DST, and MALAT1." (PMID 37745301, 2023).
MT-RNR2 also shares sentences with these, for which no sentence is quoted: age-related macular degeneration (5 papers); infection (5); prostate carcinoma (5); Obesity (4); Parkinson disease (4); macular degeneration (3); metabolic disease (3); neurodegenerative disease (3); depression (2); gastric cancer (2); Insulin resistance (2); metabolic syndrome (2); pituitary tumor (2); angina (1); atrial fibrillation (1); bladder tumor (1); Blindness (1); breast tumors (1); chronic fatigue syndrome (1); cognitive decline (1); Cognitive impairment (1); diabetic kidney disease (1); External ophthalmoplegia (1); glioma (1); hearing loss (1); hematoma (1); Huntington disease (1); insomnia (1); intrauterine growth restriction (1); malnutrition (1).
A further 14 diseases each share a sentence with MT-RNR2 in 1 paper.